MMP9 (matrix metallopeptidase 9)
Diseases named in the same sentence as MMP9 in open-access papers (continued):
Sharing a sentence is not in itself a finding about the gene and the disease.
atherosclerosis (continued). "Detailed analysis of microparticles showed that the two principle gelatinases essential for atherosclerosis progression, MMP-2 and MMP-9, were discovered on the outer side of the microparticles membrane." (PMID 27066292, 2016). "Among MMPs, gelatinase MMP-9 is particularly critical for the development of arterial lesions via its regulation of both VSMC migration and proliferation in the pathogenesis of atherosclerosis." (PMID 25651915, 2015). "In summary, our current results have showed that DEHP can be a potent inducer of atherosclerosis by increasing MMP-2 and MMP-9 expression at least through the regulations of p38 MAPK, ERK1/2, Akt, and NF-κB." (PMID 26690114, 2015). "The recent finding of Creb enhancing inflammation in a model of atherosclerosis, coupled to the contribution of Mmp9 in atherosclerotic lesion rupture and development of aortic aneurysm, suggest that Creb-like proteins might have a function in Mmp9-related vascular disease." (PMID 25359725, 2014). "Atherosclerosis is a process of chronic inflammation, and MMPs, specifically, MMP-2 and MMP-9, are the principal enzymes in extracellular matrix degradation essential for the invasion and migration of VSMCs." (PMID 24739942, 2014). "In both atherosclerotic plaques and the intima of injured vessels, lipocalin-2 colocalizes with matrix metalloproteinase 9 (MMP-9), a key protease in inflammation and atherosclerosis." (PMID 23799122, 2013). "Moreover, the expression of FOXP1 was positively correlated with SESN3 and negatively correlated with CDKN2A, MMP9, and ICAM1 in human atherosclerosis plaques." (PMID 41355963, 2026). "In animal models of atherosclerosis, myeloid cell‐specific overexpression of lncAPAT enhanced the atherosclerotic plaque lesion area, increased the ratio of type III/type I collagen, and promoted the expression of MMP9 and MMP2 in aortic plaques." (PMID 41527512, 2026). "ST analysis revealed that IGF‐1 inhibited gene expression of FOS/FOSB factors, as well as MMP9 and CXCL14 in plaque macrophages, these molecules may be involved in the IGF‐1 effect on atherosclerosis." (PMID 40156163, 2025). "Matrix metalloproteinase-9 (MMP-9) is a zinc-dependent endopeptidase capable of degrading extracellular matrix components, and its increased expression is closely related to the occurrence of atherosclerosis." (PMID 40710369, 2025). "We identified three candidate biomarkers for T2DM-related atherosclerosis—IL1B, MMP9, and P2RY13." (PMID 41516018, 2025). "Although MMP9 inhibition (by aldosterone antagonists and ACE inhibitors) represents a therapeutic approach for heart failure, atherosclerosis, hypertension, and myocardial infarction, patients with congestive heart failure demonstrate reduced Mmp9 mRNA levels in cardiac biopsies." (PMID 40869420, 2025). "In addition to its interactions with MMP9 and ADORA2A, ACE2 also showed connections with Apolipoprotein E (APOE), a protein that plays a central role in lipid metabolism and atherosclerosis." (PMID 40142959, 2025). "MMP9, DAPK1, and P2RY13 tracked by flourishing AI nomogram (LASSO, RF, and SVM) were negatively related with Macrophages M1, translating as PCOS-mediated hub genes in atherosclerosis, with the latent pathogenesis lies in inflammatory response and immunity." (PMID 40549330, 2025). "Changes in concentrations of MMP-9 and MMP-14 were found in both investigated CAD groups, with MMP-9 levels being significantly higher in obstructive CAD samples than in INOCA/ANOCA, which confirms the role of inflammation in the development of atherosclerosis." (PMID 39684689, 2024). "Besides, hinokitiol played a role in the modulation of gene related to the progression of atherosclerosis; MMP-2 and MMP-9." (PMID 36982410, 2023). "MMP9, MMP12, FABP4, and CD36 might be the potential therapeutic targets in treating atherosclerosis and NSCLC." (PMID 37978381, 2023).
atherosclerosis (continued). "We hypothesized that atorvastatin could inhibit the expression of MMP9, MMP12, FABP4, and CD36 in patients with atherosclerosis and NSCLC." (PMID 37978381, 2023). "After overlapping the 431 putative targets of atorvastatin with 15 common pathogenic genes between atherosclerosis and NSCLC, then find 4 genes (MMP9, MMP12, CD36, and FABP4) were identified as potential therapeutic targets of atorvastatin for atherosclerosis and NSCLC." (PMID 37978381, 2023). "Furthermore, we also find evidence that ETs generated from CD68+ VSMCs in three specimens from human aspiration atherosclerosis plaque and find that areas of ETs positive CD68+ VSMCs are related to MMP9 positive areas in a series adjacent section." (PMID 36473863, 2022). "Matrix metalloproteinase-9 (MMP-9), an enzyme produced by infiltrating macrophages and VSMC, has been shown to play an important character in plaque development and pathogenesis of atherosclerosis." (PMID 36465175, 2022). "The levels of neutrophil gelatinase-associated lipocalin (NGAL) which is expressed in endothelial cells and modulate the activity of matrix metalloproteinase 9 (MMP9) and also an important mediator of vascular remodeling and plaque instability in atherosclerosis." (PMID 35996626, 2022). "Significantly, in a low-grade inflammation state, such as established atherosclerosis, E2 promotes the destabilization of the atherosclerotic plaque by inducing the expression of molecules such as MCP-1 and MMP-9 and by increasing the activity of MMP-2 in the endothelial cells." (PMID 36142876, 2022). "It has been reported that in atherosclerosis, 7a-Hydroxycholesterol can elicit TLR6-mediated expression of IL-23 by monocytic cells via PI3K/Akt and MAPKs pathways, leading to inflammation via the upregulation of CCL2 and MMP-9 in macrophages." (PMID 34552973, 2021). "Although we unequivocally observed that the more advanced the atherosclerosis, the more MMP9, we did not observe that zinc, which is a key element of this and other metalloproteinases, correlated with the severity of atherosclerosis." (PMID 34202347, 2021). "Overall, our results demonstrate that C. albicans induces foam cell formation, inflammation, and MMP-9 expression in macrophages via the upregulation of FABP4, which may constitute a novel therapeutic target for treating C. albicans-induced atherosclerosis." (PMID 34829801, 2021). "In the arterial wall, accumulated macrophages secrete considerable amounts of MMP‐9 but its pathophysiological functions in atherosclerosis have not been fully elucidated." (PMID 32126159, 2020). "In this experimental model of atherosclerosis, we successfully prove and visualize overexpression of MMP-2 and MMP-9 in unstable upstream low oscillatory shear stress plaques as compared to the high laminar shear stress-induced downstream plaques and control carotids." (PMID 30304051, 2018). "Since the activation state of gelatinases seems to be of crucial importance for their function in atherosclerosis, we questioned whether the MMP‐2 and MMP‐9 produced by the SMC after co‐culture with MAC are secreted and have gelatinolytic activity." (PMID 29992758, 2018). "Our data demonstrate that obese children and adolescents present higher meanIMT values, plasma MMP-9 and MMP-9/TIMP-1 ratio compared to the non-obese.Thus, these findings indicate that this group presents a risk profile forearly atherosclerosis." (PMID 28443954, 2017). "This study demonstrated a detrimental role of TLR7 in diet-induced atherosclerosis in Apoe−/− mice by increasing lesion inflammation (MHC-II), lesion pro-inflammatory cytokine expression (IL6), lesion protease expression (CatS, and MMP-9), and systemic inflammation (plasma SAA)." (PMID 28405010, 2017).
atherosclerosis (continued). "MMP-9 and NGAL seem also to increase together the systemic inflammation which participates in atherosclerosis evolution from the early development of endothelial dysfunction, to formation of mature atheromatic plaques, to the ultimate endpoint, rupture, and thrombotic complications." (PMID 27298828, 2016). "Significant negative relationship of serum MMP-9 with HDL-C indicated the implication of serum MMP-9 concentrations in the development of atherosclerosis in arsenic-affected people." (PMID 26637202, 2015). "Our data also showed the decreased serum concentrations of MMP-9 in the stage AS1/2 of atherosclerosis in PD patients compared with CKD patients without dialysis treatment." (PMID 26538831, 2015). "Our results strongly suggest that DEHP may induce atherosclerosis development by increasing expression of MMP-2 and MMP-9 via p38 MAPK-, ERK1/2-, Akt-, and NF-κB-mediated pathways." (PMID 26690114, 2015). "We confirmed significantly lower level of serum MDA throughout all the stages of atherosclerosis in PD patients compared with observed CKD patients (P < 0.05) and increased serum concentration of MDA and MMP-9 with the progression of severity atherosclerotic changes in both groups of patients." (PMID 26538831, 2015). "Thus, MIF gene interference stabilizes atherosclerosis plaque likely by inhibiting MMP-2 and MMP-9 expression, up-regulating TIMP-1 expression and decreasing the ratio of MMP-2/TIMP-1." (PMID 25661015, 2015). "To investigate whether CCN3 is capable of regulating the inflammatory factors in atherosclerosis, we first analyzed the expression of MMP-2 and MMP-9 by ELISA." (PMID 24722330, 2014). "Indeed, our findings support that atherosclerosis development is accompanied by an increase in MMP-2, MMP-3, MMP-8, MMP-9, TIMP-1 and TIMP-2 levels." (PMID 25264981, 2014). "In this study, our data support a novel effect of curcumin on the expression level of EMMPRIN, MMP-9 and MMP-13, suggesting that curcumin could be a potential therapeutic agent for ameliorating the development of atherosclerosis plaque." (PMID 25241044, 2014). "In experimental settings, increased TIMP-1 expression has led to decreased atherosclerosis development in some but not other studies, and decreased MMP-9 expression has also led to a reduced atherosclerotic burden." (PMID 21283828, 2011). "Considering the potential connections among MMP-9, SR-BI, ABCA1 and NF-κB in related to inflammation and atherosclerosis, and the regulatory roles played by ASA in these mechanisms, we investigated the effects of ASA on the expressions of these molecules using highly relevant human macrophages." (PMID 20137092, 2010). "The literature suggested FCGR3A(CD16A) + monocytes were significantly increased in apoE-/- mice with high fat diet, which might correlate with aortic MMP-9 mRNA expression and serum TNF-α level, indicaitng FCGR3A involved in the progression of atherosclerosis through inflammatory pathways." (PMID 41348730, 2025). "Deletion of AMPKα2 in macrophages may lead to atherosclerosis through an increase in the expression of DNMT1, greater quantitative relation of SAM to SAH (S-adenosyl homocysteine), and amplified methylation of VEGF and matrix metalloproteinase-9 (MMP9)." (PMID 37998729, 2023). "The differentiating genes within the indicated criteria were genes for metalloproteinase type 9 (MMP-9) and tissue inhibitor of metalloproteinases 1 (TIMP-1), which may indicate their important role in the development of atherosclerosis and its progression and heart failure." (PMID 37893149, 2023). "Moreover, thymol has been revealed to prevent the development of atherosclerosis by suppressing inflammatory mediators: IL-1β, IL-6, TNF-α, and TNF-β and adhesion molecules: vascular cell adhesion molecule-1 (VCAM-1), MCP-1, and matrix metalloproteinase 9 (MMP-9) in hyperlipidemic rabbits." (PMID 36982410, 2023).
atherosclerosis (continued). "Interestingly, Trem2+ LAMs expressing Spp1 showed a transcriptional profile similar to osteoclasts during advanced stages of murine atherosclerosis, and human multinucleated giant cells express MAM markers such as SPP1, MMP9, CHI3L1 in granulomatous slack skin." (PMID 37706477, 2023). "In addition, they demonstrated that CB-ECFCs were able to decrease the expression of mediators of inflammation and atherosclerosis produced by allogeneic lymphocytes and monocytes (IL-1β, IL-8, PGF, ALOX-5, TNFα, CSF-2, MMP-1, MMP-9) more significantly than adult ECFCs." (PMID 32381102, 2020). "Thus, the proMMP-2 and MMP-9 that are absent in the two groups of control appear as a consequence of Met, with accentuation to NP indicating atherosclerosis status, their expression being stimulated in macrophages and vascular SMCs." (PMID 28133545, 2017). "These consistent findings suggest that in early atherosclerosis, changes in MMP-9 following treatment with T3 may not be significant enough as they are not overly expressed following HCD." (PMID 27799085, 2016). "Because MMP-9 and MMP-13 plays an important role in the rupture of atheromatous plaques, our findings shed novel insight into the regulatory mechanism of MMP-9 and MMP-13 expression, the function of AMPK, and a potential treatment of atherosclerosis by curcumin." (PMID 25241044, 2014). "Combining the ultrasonographic and histological changes of atherosclerosis, we suggested that lipids fluctuation might increase the expressions of MMP-9 and LOX-1, accordingly accelerate the progression of atherosclerosis and lead to the formation of unstable plaques." (PMID 25007151, 2014). "However, the role of MMP9 in early atherosclerosis is not well studied." (PMID 38660518, 2024). "In the present study, our results showed that curcumin significantly reduced MMP-9 and EMMPRIN expression under the stimulation of oxLDL in macrophages, which means that curcumin could be a potential therapeutic agent for inhibiting plaque rupture or retarding atherosclerosis." (PMID 28261097, 2017). "The comparison of AngII, losartan and the combinatory effect on the expression of MMP-9 and TIMP-1 in VSMCs indicated that losartan inhibited the effects of AngII, therefore reducing the MMP-9/TIMP-1 ratio, which may contribute to the molecular mechanism of losartan in preventing atherosclerosis." (PMID 25405958, 2015). "Although the presence of contralateral carotid artery stenosis did not influence the plasma levels of MMP-9 and TIMP-1 at any time point, an examination of the effects of atherosclerosis in other arteries was not part of our study." (PMID 30157791, 2018). "Depending on the stages of atherosclerosis our data showed significant changes in serum concentration of MDA and MMP-9 between the different subgroups of CKD nondialysis-dependent patients, as well as in patients on peritoneal dialysis." (PMID 26538831, 2015).
ovarian carcinoma (335 papers, 1998 to 2026). A malignant neoplasm originating from the surface ovarian epithelium. "Loss of FLNB inhibits vascular permeability and, in ovarian cancer cells, promotes MMP9-mediated tumour invasion and VEGFA-mediated angiogenesis plus induces tumour growth." (PMID 41373535, 2025). "In ovarian cancer, MMP9 has been found to be associated with tumor invasion, metastasis, and angiogenesis." (PMID 38918474, 2024). "Our study’s findings on MMP9’s co-dysregulation in both tumor and serum, along with its known associations in ovarian cancer progression, suggest its potential as a diagnostic marker for HGSOC." (PMID 38918474, 2024). "Increased levels of MMP-2 and MMP-9 are associated with the invasive and metastatic potential of malignant ovarian tumours." (PMID 37446252, 2023). "MMP9 has been found to be closely associated with metastasis in ovarian cancer and to act as an independent prognostic marker." (PMID 35645793, 2022). "Increased expression of MMP-9 was associated with poor prognosis, and its downregulation is one of the strategies used to improve the outcome of ovarian cancer." (PMID 36142326, 2022). "In fact, it has been shown that expression of MMP9 alone is sufficient to cause downregulation of E-cadherin in kidney tubular epithelial cells and ovarian cancer." (PMID 32906721, 2020). "MMP2 (72 kDa type IV collagenase) is intimately linked with the invasion and metastasis of ovarian cancer, while MMP9 (68 kDa type IV collagenase) is a useful serum marker of ovarian cancer." (PMID 32083017, 2019). "The Rg3-induced downregulation of MMP-9 is associated with the decreased invasive capacity of ovarian cancer cells." (PMID 30915362, 2019). "The results indicate that downregulation of FBLN5 in ovarian cancer was accompanied by dramatic induction of MMP-9 and loss of its inhibitor, TIMP2." (PMID 29581841, 2018). "MMP expression, particularly MMP-2 and MMP-9, has been shown to have clinical association with progression of ovarian cancer." (PMID 29891015, 2018). "Overexpression of MMP-9 attenuated E-cadherin protein level while silencing MMP-9 gene caused elevation in E-cadherin in ovarian cancer cells." (PMID 29213108, 2017). "Ovarian cancer’s poor progression is closely associated with overexpression of matrix metalloproteinase 9 (MMP-9), which belongs to the class of enzymes believed to be involved in the degradation of extracellular matrix." (PMID 28859117, 2017). "It induces MMP-9 expression and is associated with hepatocyte growth factor-mediated invasion of ovarian cancer cells." (PMID 27174914, 2016). "Gal-7 is over-expressed in lymphoma cells and is related to promoting tumorigenesis by induction of MMP9 and in ovarian cancer it is associated with cell proliferation and poor prognosis." (PMID 27558259, 2016). "PITX2-induced TGF-β pathway regulated the expression of invasion-associated genes, SNAI1, CDH1 and MMP9 (p < 0.01) that accounted for enhanced motility/invasion of ovarian cancers." (PMID 26298390, 2015). "Stable overexpression of MMP-9 led to a loss of E-cadherin and junctional integrity, and promoted a migratory and invasive phenotype in ovarian cancer." (PMID 26932374, 2014). "MMP-2 and MMP-9, in particular, have been found to be specifically associated with ovarian cancer metastasis." (PMID 23566400, 2013). "In particular, MMP-2 and MMP-9 are consistently upregulated in ovarian cancer and are associated with poor prognosis." (PMID 22022379, 2011). "It was shown that the expression of MMP-9 in ovarian cancer was significantly enhanced in tumor associated macrophages in the patients with elevated depressive symptoms and catecholamine potentiated LPS-induced expression of MMPs in human monocytes." (PMID 20939893, 2010). "The matrix metalloprotease MMP-9 localizes to tumour-associated macrophages in human ovarian cancer but little is known of its regulation." (PMID 9743290, 1998).